TG (thyroglobulin)
Diseases named in the same sentence as TG in open-access papers (continued):
Sharing a sentence is not in itself a finding about the gene and the disease.
autoimmune thyroid disease (continued). "In this setting, in other studies including patients with SA and autoimmune thyroiditis, a remarkably high incidence of positive autoantibodies against thyroid peroxidase and thyroglobulin were found." (PMID 33550991, 2021). "In thyroid autoimmunity, Danish twin cohorts have been used to calculate the heritability of GD (0.79) and of autoantibodies directed against thyroperoxidase and thyroglobulin in euthyroid subjects (0.73)." (PMID 32229696, 2020). "Diagnosis of autoimmune thyroiditis was made if anti–thyroperoxidase >35 iu/ml or anti–thyroglobulin >20 iu/ml at diagnosis of CD and then at one year on gluten free diet (GFD) in all cases." (PMID 32968394, 2020). "One example is thyroglobulin, which constitutes a target in autoimmune thyroiditis, and in which case PTM through iodination have been proposed as a mechanism leading T cells to escape tolerance." (PMID 29367624, 2018). "Anti-thyroid peroxidase antibodies (anti-TPO Ab) and anti-thyroglobulin antibodies (anti-TG Ab) are fundamental markers of thyroid autoimmunity." (PMID 29699958, 2018). "We targeted to commentate anti-thyroid peroxidase (anti-TPO), anti-thyroglobulin (anti-TG) antibody levels and thyroid autoimmunity in PCOS." (PMID 29699958, 2018). "Thyroglobulin is a main autoantigen of autoimmune thyroid diseases, including both GD and Hashimoto’s thyroiditis." (PMID 29085334, 2017). "Thyroid autoimmunity, presenting with increased thyroid autoantibody levels, anti-thyroid peroxidase (anti-TPO) anti-thyroglobulin (anti-TG) antibodies, is associated with vitamin D deficiency [serum 25(OH)D <50 nmol/L]." (PMID 29067607, 2017). "Thyroid autoimmunity was assessed by the presence of thyroglobulin (TgAb) or thyroid peroxidase antibodies (TPOAb)." (PMID 26600670, 2015). "Antithyroid peroxidase and antithyroglobulin antibodies (anti-TPO and anti-TG, respectively) were detected as markers for thyroid autoimmunity." (PMID 25237328, 2014). "While iodine is an indispensable constituent of the two major thyroid hormones T3 and T4, it contributes to the development of autoimmune thyroiditis by enhancing the antigenicity of thyroglobulin and reducing regulatory T cells." (PMID 24957380, 2014). "Thyroid autoimmune diseases are characterized by abnormal lymphocytic activation, directed against self-antigens, i.e. thyroglobulin (Tg) and thyroperoxidase (TPO)." (PMID 24355069, 2013). "Thyroglobulin (Tg) represents one of the major autoantigens for autoimmune thyroid diseases (AITD), including both GD and Hashimoto’s thyroiditis (HT)." (PMID 22654555, 2011). "All the mice that were immunized with hTg cDNA and electroporated developed a robust antibody response to mouse thyroglobulin (mTg) demonstrating the development of a de novo thyroid autoimmunity." (PMID 21559421, 2011). "All patients had evidence of active anti-thyroid autoimmunity in their serum samples but the complete panel of anti-thyroid Abs (anti-TG, anti-TPO, and anti-TSH receptor Abs) was assessed in seven patients only (Patient 1, 3, 5, 10, 11, 12, and 13)." (PMID 20426819, 2010). "Perpetuation of auto-immune thyroiditis and production of secondary renal lesions were induced by periodic injection of aqueous preparations of altered thyroglobulin." (PMID 18853201, 2009). "Two new microsatellites have recently been described in introns 29 and 30 of the thyroglobulin gene that can be useful for further linkage studies in families with autoimmune thyroid diseases." (PMID 15762980, 2005). "At present, the CTLA-4 (chromosome 2q33), thyroglobulin (or ZFAT) (8q24) and likely HLA genes (6p21.3) are the only susceptibility loci for HT and thyroid autoimmunity to be mapped." (PMID 15762980, 2005). "One such theory suggests that autoimmune mechanisms, mediated by antibodies such as anti-thyroid peroxidase (anti-TPO) and anti-thyroglobulin (anti-Tg), which are typically present in autoimmune thyroiditis, may impact the inner ear." (PMID 41155780, 2025).
autoimmune thyroid disease (continued). "The pathophysiology of Hashimoto’s thyroiditis involves the destruction of thyroid follicular cells through the action of autoantibodies, such as anti-thyroid peroxidase (anti-TPO) and anti-thyroglobulin antibodies (anti-TG), which play a key role in confirming the diagnosis of thyroid autoimmunity." (PMID 40332182, 2025). "The most common autoimmune marker was anti-nuclear antibody (ANA) (22/36, 61%), followed by lupus anticoagulant (15/30, 50%) and any one marker of autoimmune thyroiditis, namely anti-thyroid peroxidase, anti-thyroglobulin, or anti-TSH-receptor antibody (16/37, 43%)." (PMID 40313931, 2025). "Standard biomarkers include total IgE, anti-TPO, and anti-TG antibodies, as well as thyroid function tests, which are particularly important due to the well-known association of CSU with autoimmune thyroid diseases, such as autoimmune thyroid disease." (PMID 40075855, 2025). "The researchers suggested that the post-vaccination increases in TSH receptor and thyroglobulin antibodies might predict the development of autoimmunity, particularly in females with a history of autoimmune thyroid disease." (PMID 40735669, 2024). "In addition, the higher levels of baseline thyroglobulin antibodies in patients with MPN can point to the possibility of autoimmune thyroid disease." (PMID 38894738, 2024). "Third, thyroid autoimmune-related indicators, such as thyroid peroxidase antibodies and thyroglobulin antibodies, were incorporated into this study, potentially bearing relevance to the mechanistic underpinnings of dyslipidaemia in SCH during pregnancy and its associated adverse outcomes." (PMID 38212787, 2024). "Thyroid autoimmunity may result from the formation of autoantibodies that target different thyroid antigens, including thyroglobulin (TG), thyroid peroxidase (TPO), or more importantly, TSH receptor." (PMID 39707289, 2024). "Thyroglobulin autoantibody was used as a marker for autoimmune thyroiditis." (PMID 39535393, 2024). "In addition, the number of patients with autoimmune thyroid disease (18.7% vs. 30.3%, p = 0.049) and positive thyroglobulin antibodies (9.0% vs. 19.2%, p = 0.039) was lower in those with LNM compared to those without metastases." (PMID 38011178, 2023). "Autoimmune thyroid diseases (AITD), mainly Hashimoto’s thyroiditis (HT) and Graves’ disease (GD), are a consequence of loss of immune tolerance toward organ-specific self-antigens, including thyroglobulin (TG), thyroperoxidase (TPO), and the receptor for TSH1." (PMID 35140214, 2022). "Indeed, anti-thyroglobulin antibodies (TgAb) and anti-thyroperoxydase antibodies (TPOAb) can be detected in some non-autoimmune thyroid diseases, such as SAT." (PMID 34659109, 2021). "Eventually Rose purified thyroglobulin which was injected back into the very same animal from which it was derived and found not only antibodies but also inflammation in the thyroid: he had discovered autoimmune thyroiditis." (PMID 33332019, 2021). "Chronic lymphocytic thyroiditis, also known as Hashimoto’s thyroiditis, is an autoimmune thyroid disease which presents with inflammatory cell infiltration of the thyroid gland and is characterised by the production of autoantibodies to thyroglobulin (anti-TG) and thyroperoxidase (anti-TPO)." (PMID 34573074, 2021). "Third, as levels of anti-thyroid peroxidase and anti-thyroglobulin autoantibodies were not measured in our study, we cannot determine the possible role of impending thyroid autoimmunity on the association between NAFLD with thyroid function." (PMID 34456869, 2021). "Autoantibodies against thyroid peroxidase (TPOAb) and thyroglobulin (TgAb) are commonly found in the sera of patients with autoimmune thyroid diseases (AITD), and may contribute to the abnormal thyroid functions." (PMID 32256451, 2020).
autoimmune thyroid disease (continued). "Three patients without significant infections presented with isolated autoimmune thyroiditis that was associated with antibodies against thyroglobulin, thyroid-stimulator hormone receptor, and/or peroxidase." (PMID 31921117, 2019). "Even though higher prevalence of ScHt in women is unclear, it could be due to estrogen effect, higher prevalence of autoimmune thyroid diseases, and higher concentration of thyroperoxidase antibodies and thyroglobulin antibodies in females." (PMID 30029689, 2018). "Specific target proteins along the thyroid axis associated with autoimmune thyroid disease were evaluated in our study including thyroid-stimulating hormone receptor (TSH-R), 5′deiodinase, thyroid peroxidase, thyroglobulin, thyroxine-binding globulin, thyroxine, and triiodothyronine." (PMID 28894619, 2017). "We found elevated anti-thyroid antibodies, both anti-TPO and anti-TG, in 29% of the population considered at-risk for developing autoimmune thyroid disease, over 80% of whom did not have optimal 25(OH)D levels (>100 nmol/L) at baseline." (PMID 29067607, 2017). "Here, we sought to establish an experimental autoimmune thyroiditis rat model induced by bovine thyroglobulin (bTg) injection and to investigate pathological changes and variations in serum interferon-γ-inducible protein of 10 kDa (IP-10) in thyroid tissue following iodine treatment." (PMID 24707288, 2014). "Thyroid peroxidase (TPO) antibodies are detectable in ~95% of patients with Hashimoto's thyroiditis, and thyroglobulin TG antibodies are positive in approximately 60% of adult patients with chronic thyroiditis (less often in children with thyroid autoimmune disease)." (PMID 25114812, 2014). "They suggested that a portion of the HCV genome could share a partial sequence homology in a few amino acid segments with thyroglobulin and microsome, rendering HCV patients susceptible to autoimmune thyroid diseases." (PMID 23087763, 2012). "One of the elevated autoantibodies was thyroglobulin, and since autoimmune thyroid disease is probably about 10-fold more common than SLE, this result suggests that a significant proportion of the ANA positivity seen by rheumatologists is related to thyroid autoimmunity." (PMID 21366908, 2011). "Autoimmune thyroiditis, or Hashimoto's thyroiditis, can be identified by the presence of Anti-Thyroglobulin [ATG] and/or Anti-Thyroid Peroxidase [ATPO] antibodies in the serum with or without thyroid hormone abnormalities (in a euthyroid state) or clinical symptoms." (PMID 20444250, 2010). "Various thyroid autoantibodies including thyroid stimulating antibody, anti- thyroglobulin antibody and anti-thyroid peroxidase antibody, are detectable in autoimmune thyroid diseases the latter being the most sensitive test for the diagnosis and follow-up of this group of diseases." (PMID 16526964, 2006). "We previously showed that thyroglobulin, a major auto-antigen in murine autoimmune thyroid diseases, is a ligand of MR, and suggested that MR expressed by interstitial cells in the thyroid may be involved in maintaining tolerance to this Ag in normal mice." (PMID 15701168, 2005). "Fifth, we did not measure thyroglobulin antibodies, vitamin D levels, selenium status, environmental toxin exposure, mental stress (e.g., anxiety/depression), or serum iodine levels—all of which are known to be associated with thyroid autoimmunity." (PMID 40927297, 2025). "This study aimed to examine whether the autoimmune thyroid disease (AITD) autoantibodies, anti-thyroid peroxidase antibody (TPOAb), and anti-thyroglobulin antibody (TgAb), associate with hand OA and symptomatic hand OA in the Third National Health and Nutrition Examination Survey (NHANES III)." (PMID 39228802, 2024).
autoimmune thyroid disease (continued). "In the last two decades, thyroglobulin autoantibodies (TgAb) measurement has progressively switched from marker of thyroid autoimmunity to test associated with thyroglobulin (Tg) to verify the presence or absence of TgAb interference in the follow-up of patients with differentiated thyroid cancer." (PMID 28631225, 2017). "Consequently, patients present with a constellation of physical and neuropsychiatric findings (i.e. musculoskeletal complaints, depression, free-floating anxiety, memory deficits), and in cases of thyroid autoimmunity, formation of anti-bodies to thyroglobulin (Tg) and thyroid peroxidase (TPO)." (PMID 26301086, 2015). "Taken together, these data strongly suggest that the thyroglobulin gene could represent the susceptibility gene for HT and AITD on 8q24 and, therefore, be characterized as the first thyroid-specific susceptibility gene for thyroid autoimmunity." (PMID 15762980, 2005). "Thyroid autoimmunity has been referred to as the presence of antibodies to thyroid peroxidase, TSH receptor, and thyroglobulin." (PMID 39607709, 2025). "Hashimoto’s thyroiditis (HT) is the most common autoimmune thyroid disease (AITD), which is distinguished by high thyroid peroxidase antibody (TPOAb) or thyroglobulin antibody (TgAb)." (PMID 39641893, 2025). "In autoimmune thyroid diseases, CD8 + T cells are detected against both thyroid peroxidase enzyme (TPO) and thyroglobulin (TG) and mediate gland destruction." (PMID 38687448, 2024). "The following variables were considered: sex, age, autoimmune thyroid disease, TSH, thyroglobulin, thyroglobulin Ab, multifocality, bilaterality, size (≥1 cm vs. <1 cm among total patients), extrathyroidal extension, and K-TIRADS." (PMID 38011178, 2023). "Thyroglobulin autoantibodies (A-TG) and thyroid peroxidase autoantibodies (A-TPO) are markers of thyroid autoimmunity." (PMID 37706034, 2023). "Thyroid autoimmunity (TAI), defined by the presence of circulating antithyroid antibodies targeting thyroid peroxidase (TPOAb) and thyroglobulin (TgAb), is prevalent among women of reproductive age and is the most frequent cause of thyroid dysfunction." (PMID 35721757, 2022). "Both thyroglobulin (TG) and thyroperoxidase (TPO) had been found in the subepithelial immune deposits, as the main characteristic of membranous nephropathy, which may be the reason of the higher prevalence of membranous nephropathy associated with autoimmune thyroid disease." (PMID 36496400, 2022). "Previous studies showed that 5–20% of women of childbearing age are affected by Thyroid Autoimmunity (TAI) which is characterized by the presence of anti-thyroid peroxidase (anti-TPO) and/or anti-thyroglobulin (anti-TG) antibodies." (PMID 34178319, 2021). "Autoimmune thyroiditis (AIT) is characterized by the presence of anti-thyroid antibodies, which include anti-thyroperoxidase (TPO-Ab) and anti-thyroglobulin antibodies (TG-Ab), as well as lymphocytes infiltrating the interior of the thyroid gland." (PMID 32351559, 2020). "Two thyroid antibodies that are considered indicators of autoimmune thyroiditis are anti-TPO and anti-TG." (PMID 33272321, 2020). "Among the autoimmune thyroiditis group, we found the levels of anti-TPO and anti-TG were significantly higher in patients treated by interferon beta-1b compared to patients treated by fingolimod (respectively)." (PMID 33132691, 2020). "Thyroid autoimmunity (TAI) – the presence of anti-thyroid peroxidase and/or anti-thyroglobulin antibodies – affects 8–14% of reproductively-aged women." (PMID 33239046, 2020). "Autoimmune thyroid diseases are usually accompanied by the presence of anti-thyroid peroxidase (TPO), anti-thyroglobulin (Tg), and anti-thyroid-stimulating hormone receptor (TSHR) antibodies." (PMID 28536577, 2017). "Thyroid autoimmunity (TAI), which is defined as the presence of autoantibodies against thyroid peroxidase (TPO) and/or thyroglobulin (TG), is related to repeated implantation failure (RIF)." (PMID 26308040, 2015).
autoimmune thyroid disease (continued). "These autoimmune thyroid diseases are characterized by elevated serum antibodies directed against thyroid-specific antigens like thyroid peroxidase (TPO) and thyroglobulin (Tg)." (PMID 25653881, 2015). "Thyroid autoimmunity (TAI), which is defined as the presence of anti-thyroid peroxidase (anti-TPO) and/or anti-thyroglobulin (anti-TG) antibodies, is one of common autoimmunity disorders affecting 5%–20% of normal pregnant women." (PMID 26308040, 2015). "In HT, the immune system produces autoantibodies to thyroid-specific antigens, considering that thyroglobulin (Tg) and thyroperoxidase (TPO) are the two primary antigens in thyroid autoimmunity." (PMID 25328756, 2014). "Thyroid functions (fT3, fT4, and TSH) and thyroid autoimmunity (anti-thyroid peroxidase (anti-TPO), and anti-thyroglobulin (anti-Tg) antibodies) were investigated in both groups." (PMID 23118611, 2012). "It has been reported that the serum of patients with RTH is free of auto-antibodies against thyroglobulin (Tg) and thyroid peroxidase (TPO), except in rare cases where coincidental autoimmune thyroiditis is also present." (PMID 22937287, 2011). "Autoimmune thyroiditis (AIT), primarily encompassing Hashimoto’s thyroiditis (HT), is an organ-specific autoimmune thyroid disease characterized by thyroidal lymphocyte infiltration and elevated thyroid peroxidase antibody (TPO-Ab) or thyroglobulin antibody (TG-Ab) levels." (PMID 40909293, 2025). "Autoimmune thyroiditis was unlikely, as thyroid peroxidase and thyroglobulin antibodies were negative." (PMID 41446490, 2025). "Thyroid autoimmunity (TAI) is defined as the presence of thyroid peroxidase antibodies (TPO-Ab) or thyroglobulin antibodies (TG-Ab), regardless of thyroid function." (PMID 41377941, 2025). "In both patients, the laboratory workup revealed negative autoantibodies for thyroglobulin (TGAb), anti-thyroid peroxidase (TPOAb) and thyroid-stimulating hormone receptor (TSHRAb), excluding Graves’ disease or thyrotoxicosis by autoimmune thyroiditis." (PMID 39565383, 2025). "Other gene polymorphisms, interleukin-2 receptor alpha (IL2RA), forkhead box P3 (FOXP3), thyroglobulin (TG), CD25, CD40, CLEC16A, and FCRL3, among others, have been found to contribute to both thyroid autoimmunity and type 1 diabetes (Frommer and Kahaly, 2021)." (PMID 41268326, 2025). "This could potentially lead to autoimmune thyroid diseases characterized by the production of autoantibodies against thyroid peroxidase (TPO) and thyroglobulin (Tg)." (PMID 39776440, 2024). "Fourth, Serum concentrations of serum thyroid peroxidase (TPO) and thyroglobulin antibodies were not further determined to assess the prevalence of autoimmune thyroid disease." (PMID 38281045, 2024). "Thyroid autoimmunity (TAI) is the most common autoimmune thyroid disease, which is usually characterized by high expression of anti-thyroperoxidase autoantibody (TPOAb) and anti-thyroglobulin autoantibody (TgAb) and local lymphocyte infiltration." (PMID 35707546, 2022). "Forth we have not assessd other parameters for assessment of thyroid autoimmunity such as anti- thyroglobulin." (PMID 34034716, 2021). "Furthermore, Hashimoto encephalopathy in conjunction with psychiatric symptoms and thyroid autoimmunity must be excluded by thoroughly investigating the existence of antibodies against thyroid peroxidase (TPO) and thyroglobulin (TG)." (PMID 33026492, 2021). "Thyroid autoimmunity (TAI) is defined as the presence of antithyroid antibodies – anti-thyroid peroxidase (TPO-Ab) and/or anti-thyroglobulin (TG-Ab) antibodies – and is the most common autoimmune condition in women of reproductive age, with a prevalence of 8–14%." (PMID 33239046, 2020). "Therefore, antibodies to thyroglobulin (TG) and thyroperoxidase (TPO) in blood can be detected years before manifestation of autoimmune thyroid disease." (PMID 32968394, 2020).